CLIP1 (CAP-Gly domain containing linker protein 1)
Description:
Binds to the plus end of microtubules and regulates the dynamics of the microtubule cytoskeleton. Promotes microtubule growth and microtubule bundling. Links cytoplasmic vesicles to microtubules and thereby plays an important role in intracellular vesicle trafficking. Plays a role macropinocytosis and endosome trafficking.
Synonyms: CLIP-170; CYLN1; RSN; CLIP170; CLIP
Tractability: Antibody: its Gene Ontology location is reachable by antibodies, with high confidence; UniProt places it where antibodies can reach, with medium confidence. PROTAC: ubiquitination databases record sites on it; its protein half-life has been measured.
Gene: Protein-coding gene on chromosome 12 (122,271,432 to 122,422,778, reverse strand). Ensembl gene ENSG00000130779.
Subcellular location: Cytoplasm; Cytoplasm, cytoskeleton; Cytoplasmic vesicle membrane; Cell projection, ruffle
Subcellular location (Human Protein Atlas): Microtubule ends; Mid piece; Cytosol; Principal piece
Pathways (Reactome):
Cell Cycle: Amplification of signal from unattached kinetochores via a MAD2 inhibitory signal; EML4 and NUDC in mitotic spindle formation; Mitotic Prometaphase; Resolution of Sister Chromatid Cohesion; Separation of Sister Chromatids
Signal Transduction: RHO GTPases Activate Formins; RHO GTPases activate IQGAPs
Disease: Signaling by LTK in cancer
Gene Ontology:
Molecular function: microtubule binding; microtubule plus-end binding; protein binding; tubulin binding; zinc ion binding
Biological process: microtubule bundle formation; positive regulation of microtubule polymerization; cytoplasmic microtubule organization; mitotic cell cycle
Cellular component: centrosome; cytoplasmic vesicle membrane; cytosol; macropinosome; microtubule; microtubule cytoskeleton; microtubule plus-end; cell cortex; intermediate filament; kinetochore; nucleus; plasma membrane; cytoplasm; cytoskeleton; ruffle
Genetic constraint (gnomAD): Loss-of-function variants: 45 observed, 126.85 expected, observed/expected ratio (o/e) 0.35, 90% interval 0.28 to 0.46. The upper end of that interval is the gene's LOEUF score, 0.46, which puts it in group 2 of 6, group 1 being the genes least tolerant of losing a copy. Missense variants: 1,166 observed, 1,537.7 expected, observed/expected ratio (o/e) 0.76, 90% interval 0.72 to 0.8. Synonymous variants: 528 observed, 576.57 expected, observed/expected ratio (o/e) 0.92, 90% interval 0.85 to 0.98.
Homologues: Orthologues: chimpanzee CLIP1 (99% identical), macaque CLIP1 (99% identical), pig CLIP1 (94% identical), dog CLIP1 (92% identical), guinea pig CLIP1 (90% identical), mouse Clip1 (90% identical), rat Clip1 (89% identical), rabbit CLIP1 (88% identical), tropical clawed frog clip1 (61% identical), zebrafish clip1a (48% identical), Drosophila melanogaster CLIP-190 (26% identical). Paralogues in human: CLIP2 (33% identical), DCTN1 (12% identical), CLIP4 (9% identical), CLIP3 (7% identical).
Diseases named in the same sentence as CLIP1 in open-access papers:
CLIP1 is named in the same sentence as 42 diseases in open-access papers, as found by Europe PMC text mining. Sharing a sentence is not in itself a finding about the gene and the disease. The quoted sentences say what the papers report.
non-small cell lung carcinoma (5 papers, 2020 to 2024). A group of at least three distinct histological types of lung cancer, including non-small cell squamous cell carcinoma, adenocarcinoma, and large cell carcinoma. "A novel strategy using gilteritinib can overcome resistance to lorlatinib in non-small cell lung cancer with CLIP1-LTK-L650F mutation." (PMID 38575808, 2024). "The CLIP1-LTK fusion was recently discovered as a novel oncogenic driver in non-small cell lung cancer (NSCLC)." (PMID 38575808, 2024). "CLIP1-LTK fusion gene can be used as a therapeutic target of loratinib in patients with non-small cell lung cancer." (PMID 36816364, 2023). "LTK gene is not reported with any functional oncogenicity till now, but recently CLIP1-LTK fusion has been reported in non-small cell lung cancer." (PMID 37287033, 2023). "This review describes the mechanisms of targeted-drug resistance and newly identified non-small cell lung cancer targets (e.g., KRAS G12C, NGRs, DDRs, CLIP1-LTK, PELP1, STK11/LKB1, NFE2L2/KEAP1, RICTOR, PTEN, RASGRF1, LINE-1, and SphK1)." (PMID 36909198, 2023).
breast carcinoma (4 papers, 2014 to 2022). "CAP-Gly domain-containing linker protein 1 was up-regulated in stage 2 breast cancer tissues and is known to be involved in proliferation." (PMID 31945087, 2020). "Increased levels of EB1 and CLIP-170/CLIP1, two +TIP proteins, enhances paclitaxel sensitivity in breast cancer cell lines and the response to taxane-containing therapy in patients." (PMID 32823874, 2020).
lung carcinoma (3 papers, 2022 to 2024). "They further showed that treating CLIP1-LTK-positive lung cancer cells with the ALK inhibitor lorlatinib effectively inhibited kinase activity, suppressed proliferation, and induced apoptosis." (PMID 39950101, 2024). "It is well established that lung cancer patients harbour many driver gene mutations, such as K-ras, EGFR, EML4-ALK, and CLIP1-LTK, which contribute to the initiation and progression of lung cancer." (PMID 35574342, 2022). "Accordingly, several oncogenic genes have been used as biomarkers for lung cancer diagnosis; however, the sensitivities of K-ras-G12C, EGFR, EML4-ALK, and CLIP1-LTK in lung cancer patients are only 14%, 46%, 4%, and 0.5%, respectively." (PMID 35574342, 2022).
Cognitive impairment (2 papers, 2018 to 2022). Abnormal cognition is characterized by deficits in thinking, reasoning, or remembering. "The protein encoded by CLIP1 was absent from cell lines derived from these ID patients, suggesting that loss of CLIP1 function can lead to cognitive impairments." (PMID 29962938, 2018).
Hodgkins lymphoma (2 papers, 2015 to 2019). A heterogeneous group of malignant lymphoid neoplasms of B-cell origin characterized histologically by the presence of Hodgkin and Reed-Sternberg (HRS) cells in the vast majority of cases. "The two most significant ones were in the TTC32/WDR35 and CLIP1 loci, the last of which is overexpressed in Reed-Sternberg cells of Hodgkin lymphoma." (PMID 31142279, 2019). "CLIP1 encodes a protein called CAP-GLY domain containing linker protein 1, which secures endocytic vesicles to microtubules, playing a potentially important role in atherosclerosis via LDL transportation and in a range of cancers including Hodgkin’s lymphoma and anaplastic large cell lymphoma." (PMID 26683835, 2015).
acute renal failure (1 paper, 2024). "In vivo, cLip-1 delayed death in mice undergoing acute renal failure as a result of genetic deletion of Gpx44." (PMID 38659936, 2024).
autism spectrum disorder (1 paper, 2022). A spectrum of developmental disorders that includes autism, and Asperger syndrome. "The subnetwork included AS events of ROBO1 and CLIP1, both of which had neural-regulated micro-exons (exons 3–27 nt) involved in an AS interaction network associated with an autism spectrum disorder in a previous study." (PMID 35085775, 2022).
Autoimmunity (1 paper, 2022). The occurrence of an immune reaction against the organism's own cells or tissues. "For example, one of the most significant positively selected genes is CLIP1 (class II-associated invariant chain peptide), which plays a role in MHC receptor assembly and prevention of autoimmunity." (PMID 35508966, 2022).
cyst (1 paper, 2017). A sac-like closed membranous structure that may be empty or contain fluid or amorphous material. "Interestingly, knockdown of CLIP-170 or loss of Clip1/2 gene expression did cause noticeable developmental abnormalities including reduced cyst size and delayed gut organoid development." (PMID 28179500, 2017).
fatty liver (1 paper, 2024). "Overall, we found that HOPE plays an important role in alleviating fatty liver IRI by regulating the TFPI2/CLIP1/TIRAP pathway to suppress the inflammatory response in a rat model of severe fatty liver." (PMID 39617791, 2024). "However, the underlying mechanisms of HOPE in fatty liver and the effects of TFPI2 and CLIP1 in fatty liver IRI remain unclear." (PMID 39617791, 2024). "Therefore, our findings suggest that targeting the TFPI2/CLIP1/TIRAP signaling pathway with HOPE could be a potential therapeutic strategy for alleviated IRI in fatty liver transplantation." (PMID 39617791, 2024). "We obtained samples from five cases of nonfatty liver and five cases of fatty liver from clinically discarded livers, all of which underwent 8–24 h of CS before collection to confirm the changes in TFPI2 and CLIP1 molecules in human fatty liver." (PMID 39617791, 2024).
gastric cancer (1 paper, 2022). A primary or metastatic malignant neoplasm involving the stomach. "The MYOF, CLIP1, AHNAK, ANXA2, ITPRIPL2 and LEPROT genes in tissues of patients with gastric cancer were found to be altered by amplification, extensive deletion, truncating mutations, splice mutations, missense mutations, and high/low mRNA expression." (PMID 36147922, 2022). "DeLong’s tests showed that the efficiency of MYOF was significantly better than that of CLIP1 (P < 0.001) and LEPROT (P = 0.037), and a heatmap showed distinct differences in gene expression profiles between gastric cancer and normal gastric tissue." (PMID 36147922, 2022).
glioma (1 paper, 2020). A benign or malignant brain and spinal cord tumor that arises from glial cells (astrocytes, oligodendrocytes, ependymal cells). "On the other hand, a decrease of CLIP-170/CLIP1 expression correlates with patients survival in the case of glioma." (PMID 32823874, 2020).
leukaemia (1 paper, 2024). "In addition, we also found some leukaemia‐specific proteins, oncogenes (COL2A1, CLIP1, NUMA1 and GALK1), and stem cell‐regulated proteins (ACAN, VCAN, COMP and PRDX6)." (PMID 38499475, 2024).
lung adenocarcinoma (1 paper, 2020). A carcinoma that arises from the lung and is characterized by the presence of malignant glandular epithelial cells. "Another CAP-Gly domain containing linker protein, CLIP1 is a mRNA stemness index-related key gene associated with a better lung adenocarcinoma prognosis, which is involved in tumor metastasis, relapse, and drug resistance." (PMID 33575272, 2020).
lung squamous cell carcinoma (1 paper, 2022). "This is a report of lung squamous cell carcinoma patients with CLIP1-ALK fusion gene treated with ALK inhibitors." (PMID 36172736, 2022). "CLIP1-ALK fusion gene was detected by next generation sequencing (NGS) in this patient with advanced lung squamous cell carcinoma, and Alectinib and Ensartinib were taken orally on May 5, 2021." (PMID 36172736, 2022).
stomach carcinoma (1 paper, 2022). "Further bioinformatics analysis of the ASCL2 in STAD patients using the cBioPortal and GEPIA system shows that the ASCL2 may be related to CNTNAP3, CLIP1, C9orf84, ARIH2, and IL1R2 mutations and involved in stomach carcinoma prognosis, which requires further verification in future studies." (PMID 36008864, 2022).
testis cancer (1 paper, 2024). "Almost all of the top-performing genes were that of over-expression, with PMS2 in THYM; CARD11, LASP1, STIL, POLE, KMT2C, and CLIP1 in testis cancer; ERC1, WRN, OLIG2, FANCC, and ACSL6 in ACC; and SOX2 and NDRG1 in ESCA leading in performance with AUCs ranging 0.832-0.911." (PMID 38491101, 2024).
cancer (10 papers, 2015 to 2025). A tumor composed of atypical neoplastic, often pleomorphic cells that invade other tissues. "In particular, HMucBOT-2 demonstrated copy number gains in chromosomes 5 and 12 where KRAS, KMT2D, and CLIP1 are located and have been associated with cancer transformation." (PMID 40427213, 2025). "The CLIP1 (CAP-Gly-domain-containing linker protein 1) gene regulates microtubule dynamics and mediates cell migration, particularly in cancer metastasis." (PMID 40427213, 2025). "At this time, the patient underwent a repeat tumor biopsy and RNA profiling of his cancer using an NGS assay, OSU-SpARKFuse, which revealed a novel gene fusion involving FGFR2 (exons 1–16) and CLIP1 (exons 19–24)." (PMID 31371345, 2019).
tumor (9 papers, 2017 to 2024). "The predicted lower expression of CLIP1 could, therefore, lead to decreased tumor activity, something which is in line with the predicted cellular effects of the upregulated miRNAs in the BM." (PMID 36613642, 2022). "Antigens like Flotillin1/2, GRIPAP1, or CLIP1 are also expressed in non-neural tissues without a tumor association." (PMID 30038610, 2018). "Establishment of native tumor cell lines with other RET-fusions, including TRIM33-RET, CLIP1-RET, and ERC1-RET, is also warranted." (PMID 29088743, 2017).
infection (4 papers, 2018 to 2024). The state of being infected such as from the introduction of a foreign agent such as serum, vaccine, antigenic substance or organism.
CLIP1 also shares sentences with these, for which no sentence is quoted: Intellectual disability (3 papers); cholangiocarcinoma (2); osteopetrosis (2); pancreatic cancer (2); anaplastic large cell lymphoma (1); atherosclerosis (1); breast tumor (1); Chagas disease (1); diabetes (1); fibrosarcoma (1); HIV-1 infection (1); Huntington disease (1); Hypertension (1); Infertility (1); inflammation (1); major depressive disorder (1); metanephric adenoma (1); metastatic cancer (1); mucinous ovarian carcinomas (1); myocardial infarction (1); neuroblastoma (1); schizophrenia (1).